IL6 (interleukin 6)
Diseases named in the same sentence as IL6 in open-access papers (continued):
Sharing a sentence is not in itself a finding about the gene and the disease.
tumor (continued). "Chemokines and cytokines are extensively produced in the tumor microenvironment regardless of the initial triggers and mediators such as IL-1b, TNFa and IL-6 directly promoted the tumor progression in experimental models of colorectal cancer." (PMID 26859579, 2016). "IL-1 is a master cytokine which drives the expression of several inflammatory molecules such as IL-α, IL-1β, IL-6, IL-8 and others involved in tumor growth and spread." (PMID 27738319, 2016). "Recently, IL-6 has been found to promote tumor invasion and angiogenesis, in addition to proliferation and survival, but through upregulation or activation of MMP2 and MMP9." (PMID 27613828, 2016). "A panel of pro- and anti-inflammatory cytokines was examined by protein analysis of whole C3HBA tumor lysates, and apart from IL-6 all the pro- and anti-inflammatory cytokines were significantly downregulated in Chy tumors." (PMID 27329584, 2016). "Intriguingly, TNFα and TNFR1showed divergent role in inflammation-associated hepatocarcinogenesis, and for the first time, the anti-tumor function of IL6 in HCC was revealed in present study." (PMID 27556180, 2016). "It is well known that IL-6 in joint action with hypoxia supports immune evasion of tumor cells, polarizing macrophages to suppressive M2 phenotype and promoting Th17 immune response." (PMID 27630452, 2016). "Differences were also seen in the cytokine production profile from both tumor cells themselves or in serum exosomes of tumor‐bearing mice, with enhanced IL‐6 and IL‐17, and moderately decreased TNFα in 4THM versus EMT6 tumor bearers." (PMID 26725371, 2016). "Reciprocally, the decreased expression of E-cadherin was also observed in IL-6-treated mouse tumor tissues." (PMID 27769047, 2016). "TAMs produced large amounts of both MFGE-8 and IL-6, which coordinately induced tumor potential and CSC chemoresistance through STAT3 and Hedgehog signaling, the latter of which regulates normal stem cell self-renewal." (PMID 26980947, 2016). "Significantly higher IL-6 mRNA expression was also observed in the primary tumour tissues of PTC patients than the adjacent normal tissues." (PMID 27034885, 2016). "The tumor-promoting mechanism of Th17 cells is dependent on the production of IL-17A, a pro-inflammatory cytokine, that is known to promote tumor angiogenesis, stimulate tumor cells to produce IL-6, and in some murine models recruit MDSCs within tumors." (PMID 27341128, 2016). "In tumor tissue, the expression of TNF-α and IL-6 was increased both in control mice and HAI-1-deficient mice." (PMID 27612426, 2016). "In the AOM/DSS model of CAC, genetic ablation of Il6 or treatment with anti-IL-6 receptor ameliorated tumor development." (PMID 27148488, 2016). "In cancer, IL-6 is produced by several cells in a tumor and can exert its pleiotropic effects on both malignant and stromal cells." (PMID 27738330, 2016). "Nonetheless, evidence suggests that many cytokines, such as TGF- β, IL-6, IL-10, etc. exert complex effects on tumor development." (PMID 26540574, 2016). "Our in vitro data further reveals that GC cell lines over-expression Aplein and its receptor APJ, together with the other cytokines which are known to facilitate tumor metastasis and progression, including IL-1, IL6, MMP1, MMP9 and BMP-2." (PMID 27733135, 2016). "More recently, two studies demonstrated that the CSF1R and IL-6 pathways play critical roles in the migration of MDSCs to tumours microenvironments." (PMID 27368058, 2016). "The central players involved in inflammation-mediated tumor progression include IL-1β, IL-6 and TNF-α." (PMID 26896068, 2016). "We next investigated the tumor mRNA expression of some key cytokines, we observed significantly increased expression levels of IL-1β, and IL-6 in tumors from mice treated with LTD4 or PGE2 compared to vehicle treated mice." (PMID 27388564, 2016).
tumor (continued). "They find that tumor-induced IL-6 suppresses hepatic ketogenesis, and during caloric deficiency, this triggers marked glucocorticoid secretion." (PMID 27829137, 2016). "The IL-6/STAT3 pathway was also shown to increase tumor-initiating activities in murine colon and lung cancer cell lines by milk fat globulin epidermal growth factor-8 (MFGE-8)." (PMID 26980947, 2016). "Tumor burden caused a marked increase in the serum IL-6 level (p = 0.0008), and the administration of WCUP significantly decreased the IL-6 level in the serum of CT-26 tumor-bearing mice in a dose-dependent manner (F = 27.73, p = 0.0009)." (PMID 27064118, 2016). "On the other hand, IL-6 has strong procarcinogenic activity due to its role in tumor cell proliferation, survival, angiogenesis, inflammation, and metastasis." (PMID 26989335, 2016). "As expected, IL-6 was significantly decreased in both the surrounding tissues and tumor tissues in Mdr2−/−IL6−/− mice." (PMID 27589954, 2016). "We have recently shown that the autocrine production of IL-6 by naturally occurring senescent cells fosters growth of a HER2-positive tumor." (PMID 27602583, 2016). "IL6 depletion accelerated tumor development and increased tumor burden in DDB1F/F, Alb-Cre+/− mouse." (PMID 27556180, 2016). "In this respect, NF-κB provides a mechanistic link between inflammation and cancer, whereas other factors such as TNF-a and IL-6–induced signaling have been recently shown to promote tumor growth in colitic carcinogenesis." (PMID 26716648, 2016). "Resident hepatic macrophages, known as Kupffer cells (KCs), are considered as the specific tumor-associated macrophages (TAMs) of HCC, and can produce various cytokines—most importantly interleukin (IL)-6—to promote tumorigenesis of HCC." (PMID 27589954, 2016). "Our data also suggested that overexpressed MSI1 induced IL-6 secretion and promoted tumor growth, nevertheless, ablation of IL-6 by the neutralizing antibody withdrawn the malignant phenotypes." (PMID 27285760, 2016). "A previous study demonstrated that IL-6 release induces a neutrophil-dependent anti-tumor response and that IL-6 is important in helping neutrophils resist FAS pathway-induced apoptosis." (PMID 27259252, 2016). "The lungs of animals injected with the IL-6-treated cells were better colonized by tumor cells and had more fibrotic lesions compared to the lungs of animals receiving vehicle-treated cells." (PMID 27531896, 2016). "Although an in vitro study suggests that IL-6 suppresses in vitro growth of some cancer cells, IL-6/STAT3 has been shown to promote tumor progression and immune escape in a variety of in vivo models." (PMID 27006530, 2016). "Co-treatment with dabigatran etexilate and cisplatin reduced levels of pro-tumorigenic cytokines, specifically IL-6 and IL-10, in the ascites compared to vehicle-treated mice, dramatically augmenting the anti-tumor efficacy of cisplatin treatment." (PMID 27852034, 2016). "Several other adipokines, including TNF-α, IL-6, IL-8, and monocyte chemoattractant protein-1, also have important roles in tumor progression." (PMID 26751490, 2016). "This demonstrates that IL-6 is important to C3HBA tumor growth, both in Chy mice and wt siblings, although the profound difference in IL-6 can not alone explain the different growth kinetics." (PMID 27329584, 2016). "Alteration of IL6 and Twist in hepatic CSCs significantly regulates microRNA expression and eventually influences chemoresistance and tumor spreading." (PMID 27050147, 2016). "Tumor cells secrete several soluble factors such as Interleukin 6 and GM-CSF, which influence bone marrow and help in expansion of myeloid cells." (PMID 28008330, 2016). "A literature examination of the missing cytokines (IL6, IL8, LCN2, MCP1, and CCL5) indicated that most of them have indeed been implicated in tumor growth, tumor angiogenesis, or tumor invasion." (PMID 26959742, 2016).
tumor (continued). "CRS is associated with high circulating levels of several cytokines, including interleukin-6 (IL-6) and interferon-γ, and seems to correlate with high antitumor activity and high tumor burden." (PMID 27298832, 2016). "On the other hand, human IL-6 binds to both human and murine IL-6 receptor; therefore, human IL-6 expressed by tumor cells can act on murine IL-6 receptor expressed in mice." (PMID 27068103, 2016). "Fat accumulation in the bone marrow provides a niche for tumor cells promoting their proliferation by IL-6 and JAK2." (PMID 27049717, 2016). "Studies undertaken with IL-6 transgenic mice and colon-26 tumor-bearing mice that display elevated plasma IL-6 levels have demonstrated about 25 % decrease in gastrocnemius muscle weight." (PMID 27330885, 2016). "This was due to the difference between the D and S samples varying substantially between tumours: there were large increases in IL6 expression in a minority of samples while others remain largely unaffected." (PMID 27036195, 2016). "Taken together, our data strongly suggests that one possible mechanism through which RCE inhibits invasion and tumor growth involves inhibition of IL-6, IL-8 and TNF-α pathways." (PMID 26888313, 2016). "IL-6, as a multifunctional NF-κB-regulated cytokine, is a critical tumor promoter during early CRC tumorigenesis via enhancing proliferation of tumor-initiating cells." (PMID 27057094, 2016). "Both IL-6 and IL-8 have been found to promote an aggressive tumor microenvironment through activation of the STAT-3-NfKB signaling." (PMID 28203638, 2015). "Apparently, PGE2 induces the increase of tumor cells number, and this effect is dependent on cytokines and IL-6 seemed to be the most important in EAT development." (PMID 26347589, 2015). "Serum IL-6 level of W4P-LHB-NIH3T3-injected mice was significantly higher in male than in female mice, suggesting the involvement of IL-6 in gender disparity of W4P-induced tumor growth." (PMID 25645622, 2015). "IL-6 is therefore a biomarker for immune status of the tumour microenvironment and for a patient's chronic inflammation/immune suppression status in general." (PMID 25669986, 2015). "In vivo, the transfer of CD39+ CD73+ Th17 cells, polarized in vitro using TGF-β+IL-6, promoted tumor growth." (PMID 26583099, 2015). "Studies on in vitro tumour cell induced differentiation of M2 macrophages showed IL-6 dependent differentiation." (PMID 25902944, 2015). "IL-6 is a lectin, which is produced by T-cells, neutrophils, macrophages and tumor cells, and a cytokine that controls humoral immunity." (PMID 25436003, 2015). "Tumors or stromal cells expressing interleukin 6 (IL-6) have been documented to promote tumor metastasis." (PMID 26528698, 2015). "Specifically, though some tumor stroma samples were characterized by a clear TGFβ signature, others rather showed an IL6 profile, thus validating our findings concerning a possible role of IL6 in activating prostate fibroblasts in vivo." (PMID 26375444, 2015). "For instance, IL-6 secreted by tumor-infiltrating macrophages can increase the tumor-initiating capacity and drug resistance capability of neoplastic stem-like cell populations by inducing Stat3 and Hedgehog signaling." (PMID 27158195, 2015). "Combination adjuvant MNP anti-IL6 siRNA and hepatic thermal ablation significantly reduced distant tumor microvascular density (p = 0.01 vs. hepatic RFA alone)." (PMID 26154425, 2015). "RFA alone also resulted in significantly greater cellular proliferation and microvascular density in the distant MATBIII tumor compared to RFA with MNP anti-IL6 siRNA or sham treatment (p<0.05 for all comparisons)." (PMID 26154425, 2015). "The effects were systemic, as levels of thymic stromal lymphopoietin (TSLP), tumour-necrosis factor (TNF)-α and interleukin (IL)-6 were elevated in serum of tumour-free InvEE mice and increased further in tumour-bearing animals." (PMID 25575023, 2015).
tumor (continued). "Intriguingly, in vivo blocking of IL-6/STAT3 signalling by the JAK1/2 inhibitor ruxolitinib in human LNCaP xenografts showed significantly enhanced tumour size and weight." (PMID 26198641, 2015). "Tumor growth in mice was reduced by IL-6 in human prostate cancer (LnCAP) xenografts and human neuroblastoma (WAC2) xenografts." (PMID 26516076, 2015). "HMGB1 in turn activated TLR4 and elevated the pro-tumor factors IL-6 and miR-21, together with other important factors like MMP9 and miR-155, to induce carcinogenesis." (PMID 25923834, 2015). "Host immune system responds to tumor growth with elevated inflammatory cytokines (such as interleukin-6) and subsequently elevates the serum CRP levels." (PMID 26292957, 2015). "Levels of IL-6 are frequently increased in tumor patients and increases thrombopoiesis only in the presence of TPO, which drives thrombopoiesis." (PMID 25502723, 2015). "Our study shows that the microbiota, in a TLR5 signaling-dependent manner, drives the up-regulation of tumor-promoting IL-6 in the serum of tumor-bearing mice, subsequently promoting MDSC mobilization." (PMID 25897427, 2015). "Blocking the STAT3 activation by WP1066 effectively abrogated IL-6-induced Jagged-1 expression, strongly inhibited the growth of the trastuzumab resistant cells, and enhanced the anti-tumor activities of trastuzumab in the resistant cells." (PMID 25669984, 2015). "This, in turn, activates transcription of pro-inflammatory factors including COX-2, IL-6, IL-1β, and TNFα, which promote tumor growth and progression through various mechanisms." (PMID 26107623, 2015). "We also observed reduced expression of TNF-alpha and IL-6 in silibinin-treated cancer cells as well as in tumor tissues from tumor-bearing mice treated with silibinin." (PMID 26510913, 2015). "Following 21 days of tumor growth, all tumor-bearing mice had elevated levels of IL-6 in the plasma compared to control animals (p < 0.05)." (PMID 25709898, 2015). "Here, we found that HGF mRNA was predominantly expressed by CAFs and ECs while IL-6 mRNA was mainly expressed by tumor cells and by CAFs." (PMID 25849942, 2015). "In contrast, pre-treatment with NFκB inhibitor BAY 11–7082 abrogated LPS-induced IL-6 production in 4T1-conditioned BMDMs, suggesting a role for the NFκB pathway in the tumor-conditioning of BMDMs." (PMID 26177198, 2015). "Via these pathways, IL-6 trans-signaling induces the epithelial-mesenchymal transition of tumor cells that promotes invasion, metastasis, and disease progression." (PMID 26516076, 2015). "Similar to naïve mice, tumor-bearing animals, which received the CpG or CpG-siRNA constructs elaborated higher serum levels of IL-6, TNF-α, IFN-γ and IL-12p70 compared to PBS-treated controls." (PMID 26327508, 2015). "ROS production by G-MDSCs is known to be induced by several tumor-derived factors such as TGFβ, IL-6, IL-10, and GM-CSF." (PMID 26078490, 2015). "In the presence of diabody or ds-diabody, tumor cells stimulated by Ara-C induced CD8+ T cells to produce the highest amount of IL6 (diabody: 578.7 ± 52.5 pg/ml, ds-diabody: 618.8 ± 31.3 pg/ml)." (PMID 26444983, 2015). "Although further studies are needed to understand the complex roles of IL-6 signaling, completely revealing the functions of IL-6 during tumor progression will lead to new approaches for the treatment of OSCC." (PMID 25761055, 2015). "One of the most abundant cytokines released by PDT-treated tumor cells is IL-6, which is upregulated by NF-κB and AP-1 transcription factors." (PMID 26516076, 2015). "IHC analysis of the affected lungs indicated increased expression of IL-6 in tumours expressing ectopic IRAK1." (PMID 26503059, 2015). "Physiological doses of estrogen suppress HCC metastasis by decreasing interleukin-6 and hepatocyte growth factor expression in the tumor microenvironment." (PMID 26503703, 2015).
tumor (continued). "In this case, catabolic factors, such as IL-6 and TNF-α, are increased, contributing to the loss of muscle mass, and it has been suggested that the tumour has a great influence on the increase in the circulation of these factors." (PMID 26508818, 2015). "hCG-conditioned tumor cell supernatants induced heightened secretion of IL-6 and TNF-α from peripheral blood adherent cells and secreted IL-6 imparted chemo-resistance to naïve tumor cells." (PMID 26608647, 2015). "In tumor-bearing mice under chemotherapy, supplementation with fish oil and selenium prevented a rise in IL-6, TNF-α and myostatin and muscle atrophy." (PMID 25797259, 2015). "Interleukin-6 (IL-6) is one of the most critical tumor-promoting cytokines in non-small cell lung cancer (NSCLC)." (PMID 25504436, 2015). "Neither heat inactivation (to denature proteins) nor benzonase treatment (to degrade nucleic acids) impacted the ability of tumor CM to promote IL-6 production or inhibit LPS-dependent induction of TNF by BMMCs." (PMID 26343581, 2015). "IL-6 is known to participate in the immune response or tumor metastasis, and IL-8 contributes to cancer progression through its potential functions as a mitogenic, motogenic and angiogenic factor." (PMID 26076490, 2015). "There are several possible explanations for these intriguing results: A) We showed that endothelial cell-derived IL-6 is critical for tumor growth." (PMID 26287605, 2015). "Tumor-derived versican (a proteoglycan which sequesters chemokines and acts as a chemo-attractant for inflammatory cells in the tumor milieu) can stimulate resident macrophages to secrete IL-6 and TNF-α in a TLR-2 dependent manner." (PMID 26608647, 2015). "Recent studies showed that the IL-6 inflammatory feedback loop leads to CSC self-renewal and induction of EMT, both of which are implicated in tumor metastasis and poor outcomes by therapeutic resistance." (PMID 26515594, 2015). "IL-6 induces the proliferation of tumor cells proliferation, whereas IL-8 has angiogenic and chemotactic properties." (PMID 25976744, 2015). "In this study, we investigated the effect of SCL on the production of cytokines, including TNF-α, IFN-γ, IL-2 and IL-6, in H22 tumor-bearing mice." (PMID 26426041, 2015). "We investigated expression of IL6, its receptors and the IL6 signal transduction pathway in ES tumor samples and cell lines applying reverse transcriptase PCR, immunoblot and immunohistochemistry." (PMID 26215971, 2015). "A recent study provides evidence that loss of SOCS1 expression inside tumor cells via promoter hypermethylation is strongly associated with overproduction of inflammatory cytokines like TNF-α and IL-6." (PMID 25814785, 2015). "IL-6, a cytokine involved in chronic inflammation, was often reported to be present in primary and tumour cell line fluids." (PMID 25902944, 2015). "IL-6 in the tumor microenvironment is one of the most critical tumor-promoting cytokines in various cancers including NSCLC." (PMID 25504436, 2015). "Tryptase activation promotes tumor cell proliferation and neo-angiogenesis by triggering the release of interleukin 6 and granulocyte-macrophage colony-stimulating factor from MCs." (PMID 26530140, 2015). "Tumor proliferative index and microvascular density for combination nanoparticle anti-IL6 and sham arms were equivalent to each other and lower compared to the group treated with RF ablation of normal kidney alone." (PMID 26154425, 2015). "Since the main source of IL-6 secreted into the biological fluids is the tumor tissue, this study was designed to investigate the status and possible clinical relevance of the IL-6 expression in an array of EOC tissue specimens." (PMID 26282935, 2015). "Observations of IL6 action under circumstances of cell stress in other tumor cell models support our results." (PMID 26215971, 2015).